STAG2 (STAG2 cohesin complex component)
Diseases named in the same sentence as STAG2 in open-access papers (continued):
Sharing a sentence is not in itself a finding about the gene and the disease.
tumor (continued). "Here, we demonstrate that STAG2 knockout in multiple tumor cell lines resulted in hypersensitivity to ATM inhibitors, which is consistent with our screening data." (PMID 37985839, 2023). "We posit the conjecture that elevated STAG2 expression fosters catalysis of homologous recombination, thereby conferring a consequential influence on the dynamics of tumor cell growth." (PMID 37985839, 2023). "Whole-exome sequencing revealed 99 somatic mutations including SMARCA4, ARID2, TET2, CDKN2A, WNT7A, NOTCH3 and STAG2, all present both in the primary tumor and in the cell line." (PMID 38201285, 2023). "In the TCGA database, we found that the expression of STAG2 mRNA in tumor tissues was higher than that of normal colon tissue." (PMID 37985839, 2023). "Further investigation on the regulation of tumor immune evasion by STAG2 will provide insight into the tumor suppression mechanism of the cohesin complex, one of the most frequently mutated protein complexes in cancer." (PMID 35388001, 2022). "NF1 and STAG2 were the most strongly downregulated candidates with well-established tumor suppressor functions." (PMID 34967922, 2022). "Altogether, these data suggest that altered STAG2 levels in tumor tissues have different clinical consequences for patients with NMIBC and MIBC." (PMID 36275363, 2022). "In vivo, we found that KD of STAG2 protein expression decreased tumor growth rate, while overexpression of STAG2 protein accelerated tumor growth rates and led to larger tumors." (PMID 36275363, 2022). "Translational teams should determine the best, non-consumptive, correlative studies to evaluate mechanisms of resistance and relapse to advance our understanding of tumor evolution and acquired resistance with epigenetic changes from STAG2 in particular." (PMID 36115869, 2022). "Univariate Cox regression analysis showed that STAG2, SMC1B, M stage, N stage, clinical stage, and residual tumor status were significantly associated with the OS of ESCA patients (P < 0.05)." (PMID 35371307, 2022). "In mouse xenograft studies, STAG2 knockdown (KD) decelerated MIBC tumor growth, whereas STAG2 overexpression accelerated tumor growth." (PMID 36275363, 2022). "Tumor weight at endpoint was greater in the control group compared with STAG2 KD tumors [0.345 g vs. 0.220 g (shSTAG2–1, P = 0.3428) and 0.184 g (shSTAG2-2, P = 0.2035)]." (PMID 36275363, 2022). "To assess the effect of STAG2 loss on tumor growth in vivo, we performed subcutaneous bilateral injections in nude mice, such that each mouse had one control tumor and one STAG2 KD tumor." (PMID 36275363, 2022). "UM-UC-3 xenografts with STAG2 overexpression had larger tumor volumes throughout the duration of the experiment compared with tumors with empty vector (right)." (PMID 36275363, 2022). "We show that among patients with localised tumours treated with VDC/IE, STAG2 loss of expression is associated with poor outcomes independent of clinical features." (PMID 36221002, 2022). "Endpoint tumor weights were higher in STAG2-overexpressing tumors compared with tumors with empty vector (1.34 g vs. 0.78 g, P = 0.0656)." (PMID 36275363, 2022). "The STAG2 high expression group showed genes enriched mainly in aggressive tumor processes, such as angiogenesis, epithelial-mesenchymal transition (EMT), and hedgehog signaling." (PMID 35371307, 2022). "Mutations of FGFR3, STAG2, and PRKDC were significantly associated with tumor risk stage (P < 0.05)." (PMID 33407469, 2021). "Mean time for tumor development was 1.2 months (range 0.8–1.8 months) for Stag2 shRNA+10Gy cells with Stag2 knockdown and 3.1 months (range 1.6–5.5 months) for Ctrl shRNA+10Gy cells without Stag2 knockdown (p < .001)." (PMID 31898537, 2020). "LOF mutations of STAG2 are significantly elevated in metastatic breast cancer tumors when compared with lower grades, suggesting that STAG2 has a role in preventing tumor transition to malignancy." (PMID 32629605, 2020).
tumor (continued). "The release of this miRNA via EVs was able to promote tumorigenesis and epithelial-to-mesenchymal transition (EMT) through repression of Ras suppressor 1 (RUS1) and stromal antigen 2 (STAG2), well-known tumor suppressors." (PMID 30884898, 2019). "Based on these iterative findings we propose that STAG2 is a clinically significant tumor suppressor in PDA." (PMID 24484537, 2014). "These include the two patients with STAG2 somatic aberrations in the current study, one of whom had a clonal homozygous deletion in the primary tumor and two distant metastatic lesions." (PMID 24484537, 2014). "The clinical annotation available for each tumor represented on the TMA allowed the assessment of STAG2 expression relative to overall survival and responses to adjuvant therapy." (PMID 24484537, 2014). "This included one animal with sufficient tumor tissue available for resequencing from primary and multiple metastases that confirmed the clonal nature of the STAG2 insertion." (PMID 24484537, 2014). "For example, in the two confirmed cases of somatic genomic targeting of STAG2 the tumor cell content was less than 10% of the total cellular content of the biopsy." (PMID 24484537, 2014). "We then used a tissue microarray (TMA) to survey STAG2 protein expression levels in 344 human PDA tumor samples and adjacent tissues." (PMID 24484537, 2014). "In this present study we also sought to confirm the inactivation of STAG2 in those KRASG12D GEM tumors with transposon insertions within the gene to provide further evidence of a tumor suppressor role in PDA." (PMID 24484537, 2014). "The identification of STAG2 as one of the most significant tumor suppressors of KRASG12D-driven PDA in the GEM model supports an interactive role of these two genes in the development and progression of PDA." (PMID 24484537, 2014). "We then used a tissue microarray to survey STAG2 protein expression levels in 344 human PDA tumor samples and adjacent tissues." (PMID 24484537, 2014). "Our TMA-based expression analysis provides further clinical validation of a tumor suppressor role for STAG2 in PDA." (PMID 24484537, 2014). "When subdividing by stage or grade, significantly lower FGA was found in stage Ta (t-test, P = 0.006) and grade 2 (t-test, P = 0.014) STAG2 mutant tumours." (PMID 24270882, 2014). "In total, we discovered STAG2 alterations in 30 of 101 (29.7%) of EFT samples including 14 of 65 (21.5%) clinical tumor samples and 16 of 36 (44.4%) cell lines." (PMID 25010205, 2014). "Immunohistochemistry with a mouse monoclonal antibody raised against recombinant human STAG2 was used to assess STAG2 protein expression in all tumours for which formalin-fixed, paraffin-embedded (FFPE) blocks were available (n = 120)." (PMID 24270882, 2014). "Our results provide evidence for a clinically relevant tumor suppressor role for STAG2 in KRAS mutant PDA." (PMID 24484537, 2014). "Altogether, our study presents compelling evidence that berzosertib and PI-103 may be novel opportunities to investigate as precision medicine approaches for MIBC patients based on STAG2 tumor expression." (PMID 40025053, 2025). "Altogether, our study presents evidence that berzosertib, PI-103, and the combination of berzosertib with cisplatin may be novel opportunities to investigate as precision medicine approaches for MIBC patients based on STAG2 tumor expression." (PMID 40025053, 2025).
tumor (continued). "Together, these findings illuminate the landscape of STAG2-regulated genes, A/B compartments, chromatin loops, and pathways in GBM, providing important clues into the largely still unknown mechanism of STAG2 tumor suppression." (PMID 38705393, 2024). "Interestingly, patients with MIBC with STAG2-low tumors have significantly improved clinical outcomes compared with STAG2-high tumor counterparts." (PMID 36275363, 2022). "Greater tumor proliferation may partially explain why patients with lower STAG2 expression experience better outcomes." (PMID 36275363, 2022). "Mathematical modeling of tumor growth rates predicted that STAG2-overexpressed tumors would reach 1,000 mm3 in 13.6 days and 2,000 mm3 in 17.0 days, faster than control tumors which were predicted to reach 1,000 mm3 in 18.4 days and 2,000 mm3 in 23.2 days (right)." (PMID 36275363, 2022). "Because four STAG2 KD tumors were collected prior to endpoint because of the control tumor size from the bilateral injections, we used mathematical modeling to estimate tumor growth rates." (PMID 36275363, 2022). "While immunohistochemistry for STAG2 did not provide evidence for a complete loss of expression in tumor cells, 7/11 (63.6%) oligosarcomas showed a tumor cell specific loss of NF1 expression." (PMID 34967922, 2022). "In addition, patients with low STAG2 tumor expression had significantly longer PFS compared with patients with high STAG2 tumor expression (26 vs. 12 months, P = 0.036)." (PMID 36275363, 2022). "These sites are likely cell-type specific, potentially explaining why STAG2 may possess oncogenic properties in some cell contexts and act like a tumor suppressor in others." (PMID 36275363, 2022). "These H4 lines have been described previously and were chosen because the parent represented a context in which the STAG2 mutation occurred and was adapted to in a tumour rather than being CRISPR generated." (PMID 34462321, 2021). "However, the frequencies of these mutations were low in the tumor tissues (0.2% for BRCA2 and 3.1% for STAG2), suggesting subclonal events." (PMID 32914024, 2019). "We identified seven oncogenes (NRAS, EGFR, RXRA, HRAS, KRAS, AKT1, ERBB2; q<0.10) and seven putative tumor suppressor genes (ARID1A, TXNIP, CTNNB1, PIK3RI, CDKN2A, KLF5, STAG2; q<0.10) significantly regulated between tumor and control, which were formerly reported to be altered in BC." (PMID 30419021, 2018). "Tumor growth continued due to miR-409-directed inhibition of RSU1 and STAG2 tumor suppressors." (PMID 28289080, 2017). "We then performed IP-Western blot analyses on the mutant STAG2 proteins that were expressed, and showed that many tumor-derived mutations do not abolish the ability of the encoded protein to interact with cohesin." (PMID 26871722, 2016). "This experiment indicates that many tumor-derived mutations in STAG2 do not have an overt effect on chromosome count when introduced into HCT116 cells." (PMID 26871722, 2016). "To measure the effects of tumor-derived nonsense and missense mutations on sister chromatid cohesion, we enriched the HCT116 cells and STAG2 KI derivatives in mitosis by short treatment with nocodazole, then examined prometaphase chromosome spreads to analyze sister chromatid cohesion." (PMID 26871722, 2016). "Taken together, these data indicate that 67 of 307 tumours examined (21.8%) contained mutations that are predicted to adversely affect STAG2 function (truncation with or without frameshift or deletion)." (PMID 24270882, 2014).
tumor (continued). "We examined STAG2 expression in all 47 tumour cell lines by immunoblotting." (PMID 24270882, 2014). "Lower mean FGA was found in STAG2 mutant tumours (t-test, P < 0.001)." (PMID 24270882, 2014). "Thus, to our knowledge, this report represents the first description of a tumor suppressor role for STAG2 in human PDA." (PMID 24484537, 2014). "In order to investigate whether STAG2 is a tumor suppressor in human PDA, we used DNA content-based flow cytometry to sort PDA samples from 50 patients." (PMID 24484537, 2014). "There was a statistically significant loss of STAG2 protein expression in human tumor tissue (Wilcoxon-Rank test) with complete absence of STAG2 staining observed in 15 (4.3%) patients." (PMID 24484537, 2014). "This current work validates that STAG2 behaves as a tumor suppressor gene in human PDA." (PMID 24484537, 2014). "There was a broad range of signal intensities with a statistically significant loss of STAG2 expression in the tumor tissue (Wilcoxon rank test) and complete absence of STAG2 staining observed in 15 (4.3%) patients." (PMID 24484537, 2014). "Of the 15 tumours with nonsense or frameshift mutations, 11 showed no detectable STAG2 protein, 2 showed positive staining and 2 contained both positive and negative areas." (PMID 24270882, 2014). "Furthermore, knockout of STAG2 inhibited tumor growth in vivo after the treatment with PARPi." (PMID 37985839, 2023). "Therefore, STAG2 appears to function as a tumor suppressor gene in the affected tissues." (PMID 32467316, 2020). "Taken together, these data suggest that unlike in the case of most tumor suppressor genes, mutational inactivation of STAG2 may have an adverse effect on proliferation." (PMID 26871722, 2016). "Though we find EFT to have a low rate of aneuploidy overall in our comprehensively characterized WGS cohort, further work is indicated to clarify whether or not a STAG2 mutation is linked to increased aneuploidy in this tumor histology." (PMID 25010205, 2014). "For example, a comparison of GIs with STAG2 KO in 3 different cell lines found only one interaction common to HAP1, RPE1, and tumor-derived H4 cell lines." (PMID 38478595, 2024). "CAF-derived EVs can also inhibit translation of tumor-suppressor genes (e.g., RSU-1, Ras suppressor 1 and STAG2, stromal antigen 2) and promote EMT via increased expression of vimentin and β2-M." (PMID 36671452, 2022). "Using a variety of experimental approaches and cell lines, we show that STAG1 and STAG2 are synthetic lethal partners and provide evidence that STAG1 is a potential therapeutic target in tumours where STAG2 is inactive." (PMID 28430577, 2017). "Having shown that many STAG2 mutations do not abrogate the ability of STAG2 to interact with cohesin, we next hypothesized that tumor-derived mutations in STAG2 might instead lead to generalized abnormalities in the subunit composition of the cohesin complex itself." (PMID 26871722, 2016).
tumor (continued). "Age did not impact the effects of inactivation of Stag2, Setd2, Cdkn2c and Rbm10 in either context, further suggesting that age interacts with specific tumor suppressor pathways as opposed to generically weakening the effects of driver mutations." (PMID 41188600, 2025). "Importantly, we also identified stromal antigen 2 (STAG2), which serves as a tumor suppressor and an accessory protein of cohesin complexes." (PMID 38747635, 2024). "Given that the knockout of STAG2 sensitized tumor cells to ATMi and PARPi, we hypothesized that ATM inhibition may synergize in vitro and in vivo with PARP inhibition to promote tumor cell killing." (PMID 37985839, 2023). "Our results suggest that in the context of MIBC, STAG2 should not be classified as a tumor suppressor." (PMID 36275363, 2022). "In the present study, we discovered overexpressed STAG2 might promote EAC progression and metastasis through facilitating tumor vascularization and EMT." (PMID 35371307, 2022). "The efficiency of tumor formation was 91% for cells in mice injected with Stag2-repressed cells and 22% for mice receiving cells without Stag2 inhibition (p < .001)." (PMID 31898537, 2020). "Some studies demonstrated that miR-154-5p could act as a tumor suppressor gene through targeting CCND2, STAG2, E2F5, HMGA2 and TLR2." (PMID 30266084, 2018). "Here we identify STAG1 as a strong genetic vulnerability of cells lacking the major emerging tumor suppressor STAG2." (PMID 28691904, 2017). "In this tumour type, transcriptional analysis of paired cell lines with and without STAG2 expression revealed no expression differences." (PMID 24270882, 2014). "Together, our data from IHC analyses suggests that STAG2 does not play a role in tumor apoptosis, but may possibly influence tumor proliferation." (PMID 36275363, 2022). "Furthermore, our results imply that the current cGAS or STING ligands under development for treating or serving as adjuvants in certain cancers will likely not work in tumor types defective in STAG2 and the cytosolic DNA-sensing pathway." (PMID 29662124, 2018). "The effects on splicing were exon skipping and/or use of local cryptic splice sites except in one tumour (1345) in which no STAG2 RT-PCR products could be detected, although control RT-PCR showed that there was adequate RNA in the sample." (PMID 24270882, 2014). "However, STAG2 and RAD21 have not been reported to affect tumor metastasis directly." (PMID 35371307, 2022).
infection (8 papers, 2010 to 2022). The state of being infected such as from the introduction of a foreign agent such as serum, vaccine, antigenic substance or organism. "We found that STAG2-deficient cells inhibited infection with vesicular stomatitis virus (VSV) and PDCoV, whereas restoration of STAG2 expression in STAG2-depleted (STAG2−/−) IPEC-J2 cells line restored PDCoV infection, suggesting that STAG2 is involved in the PDCoV replication." (PMID 36016405, 2022). "PDCoV infection was significantly inhibited in the STAG2−/− cells compared with the infection in the WT cells, according to the IFA, demonstrating that PDCoV was reduced in the absence of STAG2." (PMID 36016405, 2022).
hematologic malignancies (3 papers, 2017 to 2023). "STAG2 is the most frequently mutated in solid cancers, and in hematologic malignancies, genes including STAG1, STAG2, RAD21, SMC1A, and SMC3 are frequently mutated." (PMID 35509102, 2022). "Because the coexistence of a driver clone and the acquisition of additional mutations have been identified repeatedly in hematologic malignancies, further studies are required to elucidate how SH2B3—GATA1 and NOTCH1—STAG2 mutations contribute to the pathogenesis of hypereosinophilia." (PMID 29088303, 2017).
autosomal dominant disease (1 paper, 2022). Autosomal dominant form of disease. "STAG2 has been reported to escape X-inactivation, suggesting that disease onset in LoF females is dependent on inadequate dosing for at least some of the transcripts, as is the case with a part of the autosomal dominant diseases." (PMID 35887945, 2022).